FST (follistatin)
Diseases named in the same sentence as FST in open-access papers (continued):
Sharing a sentence is not in itself a finding about the gene and the disease.
tumor (continued). "Longitudinal monitoring of FST and FSTL3 in serum, regularly tracked during tumor growth, revealed a similar upward trend for both proteins over time." (PMID 41029436, 2025). "Quantification in cell lines confirmed the knockout of FST and low expression of FSTL3, while in tumors, FST and FSTL3 expression were significantly higher in KPCA.FSTKO tumors, indicating stromal-derived expression within the tumor microenvironment." (PMID 41029436, 2025). "Evidence suggests that Activin A can regulate the malignant phenotype of tumor cells through signaling pathways such as SMAD, PI3K-AKT, and ERK, and follistatin (FST) is its specific antagonist." (PMID 41008625, 2025). "Only follistatin and MIA significantly (p ranging from 0.04 to < 0.0001) correlated with tumor size and myometrial invasion depth." (PMID 39511039, 2024). "Nevertheless, FST represents a novel modulator of the complex EGFR–TGF-β–p63 axis and the tumor microenvironment in HNSCC." (PMID 37492374, 2023). "The effectiveness of using a combinational therapy including SeNPs, MSCs, and LDR was elucidated by measuring the expression of some genes including Serpin, MIF, LOX-1, COL1A1, FST, and ADRP that play a role in the tumor microenvironment." (PMID 35138531, 2023). "We conclude that HPV16 was most prevalent in the cervical lesions of the unvaccinated population herein investigated and that βA-activin and follistatin IRS decrease in pre-neoplastic and neoplastic diseases of the human cervix, predominantly positive for HPV." (PMID 37243119, 2023). "The follistatin over-expressing hUC-MSC (5 × 105) were intravenously administered 6, 13, and 20 days after the tumor cell’s inoculation." (PMID 35955703, 2022). "We investigated Activin A and Follistatin in serum and tumor tissue of patients with TETs in relation to microvessel density (MVD), WHO histology classification, tumor stage and outcome." (PMID 31757999, 2019). "Most importantly, Follistatin correlated significantly to MVD, which in turn was significantly different according to WHO subtype and Masaoka – Koga tumor stage." (PMID 31757999, 2019). "We managed to link the pro-angiogenic function of Follistatin with MVD and further to demonstrate that tumor vessel subtypes differ significantly according to WHO classification." (PMID 31757999, 2019). "Two tumor suppressor genes, ADRP and FST, which were up-regulated in rat UCMSC but down-regulated in human UCMSC were further characterized as potential candidate genes to exhibit stronger tumoricidal activity in rat UCMSC than in human UMCSC." (PMID 25942583, 2015). "As an activin binding protein, FST can inhibit the function of activin A, and imbalance of activin A and FST expressions is one of the important factors for tumor genesis." (PMID 25347573, 2014). "While cancer cells express FST/FSTL3, our scRNAseq and spatial transcriptomic analyses suggest that tumor stromal cells may be the predominant source of this factor in the TME." (PMID 41029436, 2025). "Furthermore, through correlation analysis, we demonstrated that concentrations of BMP-9, FAP, follistatin, MIA, and VEGF-A significantly (p ranging from 0.041 to 0.0012) correlate with tumor size (measured in cm)." (PMID 39511039, 2024). "However, unlike the in vitro assays for cell proliferation and migration, knockdown of FST in either the PC3 cells, or both cell types, reduced tumour growth to a similar degree." (PMID 36608258, 2023). "In the FST-positive IPNB/IPMN cases (57.9%), tumor cells were positive for FST focally, not entirely, and FST-positive cells tended to have slightly oncocytic cytoplasm (data not shown)." (PMID 32424306, 2020). "Follistatin serum levels showed a significant negative correlation with absolute number of immature tumor vessels, and a significant positive correlation with mature tumor vessels." (PMID 31757999, 2019).
tumor (continued). "As a consequence, additional factors in the tumor CM control myotube size and their negative effects are hampered by mechanical stimulation independently of follistatin release from myotubes." (PMID 31068826, 2019). "Follistatin serum levels showed a significant negative correlation with the number of immature (r: −0.443; p = 0.014) tumor vessels." (PMID 31757999, 2019). "Preoperative Follistatin but not Activin A serum concentration was significantly different according to Masaoka - Koga tumor stage (p = 0.037 and p = 0.988; respectively)." (PMID 31757999, 2019). "In contrast to the lack of effect of the FST transgene on tumor initiation, a major impact on metastatic progression was observed." (PMID 28583174, 2017). "In this context, the growth factor follistatin (FST) has garnered considerable attention and interest as an intriguing target across various cancers, prompting the need to explore its oncogenic role in the tumor milieu and the FST-dependent molecular events that govern cancer biology." (PMID 38392348, 2024). "Given the complex biochemical properties of FST, its function in crucial developmental processes, and its intimate association with TGF-β signaling, it is not surprising that a major role for FST in various aspects of tumor biology and treatment has been unearthed recently." (PMID 38392348, 2024). "However, the strength of the study is that we could link the pro-angiogenic function of Follistatin to MVD in TETs, which corresponds to Masaoka-Koga tumor stage and outcome." (PMID 31757999, 2019). "Correlation studies showed significant strong positive correlations for tissue activin-A and follistatin, and a significant inverse correlation for tissue activin-AB with the numbers and surface areas of large and flat ACF, MDF, adenocarcinoma as well as the numbers of gross and micro-tumours." (PMID 27835986, 2016). "Interestingly tissue levels of Follistatin differed between non-responders and responders, when defining responders as having less than 50% remaining tumor cell mass (p = 0.015)." (PMID 25885021, 2015). "Defining histopathological non-responding patients as having more than 50% remaining tumor cell mass in histopathological analysis, histopathological non-responders showed lower tissue levels of Follistatin than patients with more than 50% remaining tumor cells (p = 0.015)." (PMID 25885021, 2015). "It is interesting to note that FST expression was increased in the stromal cells of FIB, while FLRG was up regulated in IDC, indicating that the two activin binding proteins may play diverse roles in tumor progression." (PMID 19740438, 2009). "Further studies described follistatin, an intrinsic inhibitor of Mstn and Activin A, as a metastases suppressor in a HER2-positive BC mouse model, supporting our hypothesis that antibody-mediated inhibition of Mstn may affect tumor growth in the xenograft BC model." (PMID 41249489, 2025). "We identified Follistatin (FST), a secreted glycoprotein and inhibitor of transforming growth factor TGF-β/Activin signaling pathways, as a p63 target in the epithelial component of the tumor microenvironment (TME) that might play a role in directing stemness and metastasis in HNSCC." (PMID 37492374, 2023). "FGF17, natriuretic peptide A (NPPA), SHC2, and WAP, follistatin/kazal, immunoglobulin, kunitz, and netrin domain containing 1 (WFIKKN1) was not expressed or at a minimal level in tumor tissues." (PMID 34335699, 2021). "Mechanical stimulation counteracts the negative effect of tumor-derived factors on P-SMAD transcriptional targets (MRF) and on Follistatin expression." (PMID 31068826, 2019). "However, given the intimate link between FST and TGF-β and the dual role of TGF-β acting as both tumor suppressor and promoter, it is not surprising to find conflicting outcomes upon FST dysregulation." (PMID 38392348, 2024).
tumor (continued). "This adds FST to the short list of metastasis suppressor genes, such as breast cancer metastasis suppressor-1 (BRMS1), cadherin-1 (CDH1), and nucleoside diphosphate kinase 1 (NM23), that inhibit metastasis formation without impacting primary tumor growth." (PMID 28583174, 2017).
cancer (56 papers, 2007 to 2025). A tumor composed of atypical neoplastic, often pleomorphic cells that invade other tissues. "We then evaluated the expression profile of FST across the different cellular clusters and found that FST transcripts were predominantly localized to the epithelial subclusters, with sparse expression in cancer-associated fibroblasts." (PMID 37492374, 2023). "The follistatin (FST) family of secreted glycoproteins are increasingly associated with different types of cancers." (PMID 34425560, 2021). "We evaluated the association of circulating follistatin levels at baseline with incident T2D in the Malmö Diet and Cancer Cardiovascular Cohort (MDC-CC)." (PMID 34759311, 2021). "In humans, FST has been implicated in the pathogeneses of prostate, ovarian, and liver cancers, and hyperglycemia." (PMID 32134197, 2020). "Follistatin is associated with the development, progression and metastasis of various cancers." (PMID 36608258, 2023). "Dot plot analysis demonstrated that FST and FSTL3 were expressed in stromal cell populations of cancer-associated mesothelial cells (CAMC) and cancer-associated fibroblasts (CAF), at a higher level than in cancer cells." (PMID 41029436, 2025). "Only in the non-cancer group, sHER-2neu and follistatin were significantly higher in the cystic fluid." (PMID 40940878, 2025). "We next investigated the spatial pattern of expression of FST/FSTL3 to understand the relative contributions of cancer cells and stromal cells to their secretion in the TME." (PMID 41029436, 2025). "Data on FST function inCSCs are more limited, but some reports demonstrate that FST secretion from cancer-associated fibroblasts (CAFs) enhances CAF-mediated cancer cell proliferation and metastasis." (PMID 40277903, 2025). "Among these, genes positively associated with mitogenic activities and cancer progression include FGF5, FOSL1, and FST (endcoding follistatin that belongs to the TGF-β superfamily)." (PMID 38612755, 2024). "With the knowledge that growth factors induce FST expression in keratinocytes, it is essential to understand how the secretion of FST and such factors by CAFs contributes to the diminished responsiveness of cancer cells to TGF-β." (PMID 38392348, 2024). "In this study, we identify FST as a key regulator of prostate epithelial/cancer cell‐fibroblast intercellular communication, highlighting it as a potential target for therapeutic intervention." (PMID 36608258, 2023). "Contrarily, follistatin secretion was completely abolished in the C3948–macrophage co-culture, when compared with the cancer cell monoculture." (PMID 37686663, 2023). "In conclusion, activins and follistatin displayed stage-dependent dysregulations and were markedly altered during the advanced stages of right-sided and L-S4 cancers." (PMID 34867090, 2021). "In conclusion, this study showed the differences in cancer pathway activation pattern, FST expression, and apoptotic rate between IOPN and IPMN/IPNB specimens." (PMID 32424306, 2020). "As FST is an antagonist of activin during embryonic development and cancer pathogenesis, we examined the expression and role of activin in AML cell lines." (PMID 32134197, 2020). "The second mechanism would require close proximity of cancer cells and osteoblasts because a previous study has shown that most circulating activins are bound by their endogenous antagonist follistatin." (PMID 30348200, 2018). "Although FST originally has been found in the ovarian follicular fluid, recent reports implicate its role in the regulation of various types of cancer development and/or prevention." (PMID 22685544, 2012). "Growing evidence suggest deregulation of follistatin and activin to contribute to cancer development and metastasis." (PMID 19812696, 2009). "Networks with cancer-related functions had the highest significance, however reproductive networks containing follistatin and FSH were also significantly affected, which confirmed NASP's important role in reproductive tissues." (PMID 19439102, 2009).
cancer (continued). "High-throughput technologies, such as proteomics, scRNA-seq, and spatial transcriptomics (transcriptomic profiling of individual cells within their native tissue architecture), have begun to unravel our understanding of the role of FST in cancer as a potent inhibitor of the TGF-β pathway." (PMID 38392348, 2024). "Given that the super-enhancer landscape undergoes significant reprogramming in cancer, exploring differential enhancers active in tumors can shed light on how epigenetic events may contribute to the dysregulation of FST in HNSCC." (PMID 38392348, 2024). "Finally, we offer a snapshot of evolving molecular mechanisms and signaling pathways that control the aberrant expression of FST in cancer cells." (PMID 38392348, 2024). "In this review, we describe the structure, function, and expression profile of FST; its emerging role in governing key hallmarks of cancer; and highlight recent findings related to FST in the context of drug resistance and cancer progression in a number of solid tumors." (PMID 38392348, 2024). "Additionally, future cancer-centric experimental designs need to consider the diverse biochemical properties of FST, such as a differing affinity for TGF-β ligands, the relative abundance of varying FST isoforms, and post-translational variants." (PMID 38392348, 2024). "However, producing large quantities of engineered recombinant human FST as anti-cancer therapy has proven difficult." (PMID 38360876, 2024). "Follistatin (FST) is a potent neutralizer of the transforming growth factor-β superfamily and is associated with normal cellular programs and various hallmarks of cancer, such as proliferation, migration, angiogenesis, and immune evasion." (PMID 38392348, 2024). "Moreover, cancer cell–derived FST and PARD6B were positively correlated with CD31+ CD73mid endothelial cell (CD31) density, indicating that these genes modulate endothelial cell activity and subsequently angiogenesis." (PMID 33917869, 2021). "Follistatin IHC scores were also higher in the advanced than early stages of cancer (p < 0.0001)." (PMID 34867090, 2021). "Another interesting gene that we have found upregulated is FST, an intrinsic inhibitor of activin; its encoded protein, together with ACVR2B (known as ActRIIB), may inhibit cancer cell growth via antagonizing activin signaling in our cell model." (PMID 31665064, 2019). "Analysis of the cell secretome revealed specific cell-type differences (MDA-MB-231 cells: increased cancer attenuator follistatin and reduced pro-inflammatory cytokines IGFBP-1, MCP-1, MIP-1α, IL-6; MCF7: increased cancer signals osteopontin, sHER-2, VEGF-A, uPA, EGF amongst others)." (PMID 30603045, 2018). "Given the potential impact of activin on cancer progression, as well as the ability of FST to block the binding of activin to its receptor, we postulated that FST may act as a metastasis suppressor." (PMID 28583174, 2017). "Ectopic expression of BRCA1 in ovarian cells may induce the expression of FST and this FST expression in turn plays an antagonistic role to inhibit the cancer promoting function of activin." (PMID 22685544, 2012). "Although whether activins work similar to TGF-β is not currently known, despite the anti-proliferative actions of activin, follistatin seems to act as an inhibitor of cancer metastasis." (PMID 19740438, 2009). "However, questions persist about whether this mechanism is operational in epithelial cells and why there is a frequent co-occurrence of aberrant TGF-β and FST expression in cancer." (PMID 38392348, 2024). "Therefore, determining whether targeting FST can improve the effectiveness of drug therapy in LUSCC requires careful validation using cancer subtype-specific models." (PMID 38392348, 2024). "Consequently, there may be no decrease in the magnitude of the extracellular neutralization of activin function by follistatin as cervical lesions progress into cancer." (PMID 37243119, 2023).
cancer (continued). "In conclusion, activins and follistatin are pathologically altered in CRC and their deregulations were more pronounced in advanced right-sided tumours and with the loss of Smad4 protein, suggesting their important contribution to cancer development and aggressiveness." (PMID 34867090, 2021). "In contrast, activin A (Inhba), one of the main ligands bound by both FST and FSTL3 was primarily secreted by cancer cells, while its type II receptors (Acvr2a, Acvr2b) were highly expressed in both cancer cells and fibroblasts (Log2 FC > 0.5)." (PMID 41029436, 2025). "In contrast, co-culture models have shown that FST secreted from both cellular compartments supports CAF-mediated metastasis and cancer cell proliferation." (PMID 38392348, 2024). "Secreted factors such as MIF, IL‐6, CD40L, FST, SDF‐1α and IL‐8 were expressed at higher levels in conditioned medium from PC3 cancer cells." (PMID 36608258, 2023). "Notwithstanding, we demonstrated that follistatin had higher nuclear immunoscore in the control group and that it decreased, in a cellular-dependent way, with progression from CIN lesions to cancer." (PMID 37243119, 2023). "Although the roles of other genes involved in the prognostic model have been relatively less explored, some bioinformatics analyses have identified the prognostic role of some of these genes, such as RTN4R, FCGBP, and FST, in OSCC or other types of cancers." (PMID 36185403, 2022). "As secreted follistatin-module-containing glycoproteins, several FSLT members, covering FSTL1 and FSTL5, have been discovered to participate in cancer cell growth, stemness, chemoresistance, invasion, and migration." (PMID 34555811, 2021). "The prognostic value of FST and its family members, the follistatin-like (FSTL) proteins, have been studied in various cancers." (PMID 28583174, 2017). "The results found that mRNA expression of RRM2, but not FST, was significantly higher in cancer tissues than that in normal tissues." (PMID 31936661, 2020). "Some of the implanted cancer cell lines were in their original form, some were engineered to express INHBA, and some were engineered to express the activin antagonist follistatin (FST)." (PMID 22208948, 2011). "Considering that FST expression is regulated by TGF-β signaling and the likelihood that cancer cells often become unresponsive to TGF-β as oncogenesis progresses, it becomes apparent that additional mechanisms must come into play to sustain high levels of FST expression in cancer." (PMID 38392348, 2024). "DMBA-induced mammary gland carcinoma as marked by an elevation of mRNA level of cancer promoter genes (Serpin and MIF, LOX-1, and COL1A1) and serum level of VEGF, TNF-α, TGF-β, CA15-3, and caspase-3 with the reduction in mRNA level of suppressor gene (FST and ADRP)." (PMID 35138531, 2023). "One study in cancer cells identified non-miRNA-mediated regulation of the FST 3′UTR." (PMID 33420269, 2021). "Furthermore, the transfections of cancer cells with either INHBA (labeled I) or FST (labeled F) did not have any effect on the presence of the signature (the corresponding expression levels were consistent with the transfections and did not affect the expression of the other genes in the signature)." (PMID 22208948, 2011).